HEATR6 (HEAT repeat containing 6)
Description:
Amplification-dependent oncogene.
Synonyms: ABC1; FLJ22087
Tractability: PROTAC: ubiquitination databases record sites on it; its protein half-life has been measured.
Gene: Protein-coding gene on chromosome 17 (60,041,008 to 60,078,932, reverse strand). Ensembl gene ENSG00000068097.
Subcellular location (Human Protein Atlas): Mitochondria
Gene Ontology:
Molecular function: RNA binding
Genetic constraint (gnomAD): Loss-of-function variants: 69 observed, 95.56 expected, observed/expected ratio (o/e) 0.72, 90% interval 0.59 to 0.88. The upper end of that interval is the gene's LOEUF score, 0.88, which puts it in group 3 of 6, group 1 being the genes least tolerant of losing a copy. Missense variants: 1,069 observed, 1,198.1 expected, observed/expected ratio (o/e) 0.89, 90% interval 0.85 to 0.94. Synonymous variants: 433 observed, 461.85 expected, observed/expected ratio (o/e) 0.94, 90% interval 0.87 to 1.01.
Homologues: Orthologues: chimpanzee HEATR6 (99% identical), pig HEATR6 (89% identical), dog HEATR6 (89% identical), macaque HEATR6 (87% identical), rabbit HEATR6 (86% identical), guinea pig HEATR6 (86% identical), mouse Heatr6 (84% identical), rat Heatr6 (84% identical), tropical clawed frog heatr6 (64% identical), chimpanzee HEATR6 (60% identical), zebrafish heatr6 (54% identical), Drosophila melanogaster CG16989 (25% identical).
Diseases named in the same sentence as HEATR6 in open-access papers:
HEATR6 is named in the same sentence as 7 diseases in open-access papers, as found by Europe PMC text mining. Sharing a sentence is not in itself a finding about the gene and the disease. The quoted sentences say what the papers report.
hepatocellular carcinoma (1 paper, 2022). A malignant tumor that arises from hepatocytes. "In hepatocellular carcinoma cells, SCAMP3 knockdown has been shown to suppress cell proliferation, while HEATR6 has never been associated with tumorigenesis." (PMID 35453681, 2022).
psoriasis (1 paper, 2022). An autoimmune condition characterized by red, well-delineated plaques with silvery scales that are usually on the extensor surfaces and scalp. "Of interest, we identified 3 overlapping DEGs (HEATR6, HLA-DRB5, and MRPL54) between psoriasis neutrophils with and without stimulation of keratinocytes in relative to healthy neutrophils." (PMID 35401573, 2022).
tumor (2 papers, 2014 to 2021). "In addition, four genes (CDC20, UCK2, HEATR6, and SLC9A3R2) were concordantly associated with both survival duration and tumor progression (3.2)." (PMID 34858848, 2021).
HEATR6 also shares sentences with these, for which no sentence is quoted: cancer (1 paper); endometrial cancer (1); lung adenocarcinoma (1); lymph node metastasis (1).